MSANTD7 (Myb/SANT DNA binding domain containing 7)
Gene: Protein-coding gene on chromosome 10 (14,838,302 to 14,846,999, forward strand). Ensembl gene ENSG00000284024.
Genetic constraint (gnomAD): Loss-of-function variants: 23 observed, 29.91 expected, observed/expected ratio (o/e) 0.77, 90% interval 0.55 to 1.09. Missense variants: 381 observed, 475.91 expected, observed/expected ratio (o/e) 0.8, 90% interval 0.74 to 0.87. Synonymous variants: 172 observed, 181.65 expected, observed/expected ratio (o/e) 0.95, 90% interval 0.83 to 1.08.
Homologues: Orthologues: dog MSANTD7 (94% identical), pig MSANTD7 (91% identical), rabbit MSANTD7 (90% identical), guinea pig MSANTD7 (90% identical), mouse Msantd7 (86% identical), rat Msantd7 (82% identical), Drosophila melanogaster meso18E (17% identical), zebrafish si:dkey-261j15.2 (11% identical). Paralogues in human: MSANTD2 (20% identical), UTF1 (18% identical).